ANKRD13C (ankyrin repeat domain 13C)
Description:
Acts as a molecular chaperone for G protein-coupled receptors, regulating their biogenesis and exit from the ER.
Synonyms: DKFZP566D1346; dJ677H15.3
Tractability: PROTAC: ubiquitination databases record sites on it.
Gene: Protein-coding gene on chromosome 1 (70,258,999 to 70,354,734, reverse strand). Ensembl gene ENSG00000118454.
Subcellular location: Endoplasmic reticulum membrane
Gene Ontology:
Molecular function: protein binding; protein carrier chaperone; signaling receptor binding
Biological process: cellular response to prostaglandin D stimulus; protein targeting to membrane; regulation of anoikis
Cellular component: endoplasmic reticulum; perinuclear region of cytoplasm; endoplasmic reticulum membrane
Genetic constraint (gnomAD): Loss-of-function variants: 9 observed, 34.95 expected, observed/expected ratio (o/e) 0.26, 90% interval 0.15 to 0.45. The upper end of that interval is the gene's LOEUF score, 0.45, which puts it in group 1 of 6, group 1 being the genes least tolerant of losing a copy. Missense variants: 409 observed, 535.06 expected, observed/expected ratio (o/e) 0.76, 90% interval 0.7 to 0.83. Synonymous variants: 184 observed, 199.39 expected, observed/expected ratio (o/e) 0.92, 90% interval 0.82 to 1.04.
Homologues: Orthologues: chimpanzee ANKRD13C (99% identical), macaque ANKRD13C (99% identical), rabbit ANKRD13C (97% identical), pig ANKRD13C (97% identical), guinea pig ANKRD13C (93% identical), mouse Ankrd13c (92% identical), rat Ankrd13c (92% identical), dog ANKRD13C (89% identical), tropical clawed frog ankrd13c (85% identical), rat LOC102553980 (83% identical), zebrafish ankrd13c (79% identical), Drosophila melanogaster CG5742 (48% identical), and 1 more. Paralogues in human: ANKRD13A (32% identical), ANKRD13B (30% identical), ANKRD13D (30% identical).
Diseases named in the same sentence as ANKRD13C in open-access papers:
ANKRD13C is named in the same sentence as 1 disease in open-access papers, as found by Europe PMC text mining. Sharing a sentence is not in itself a finding about the gene and the disease. The quoted sentences say what the papers report.
melanoma (1 paper, 2021). A malignant, usually aggressive tumor composed of atypical, neoplastic melanocytes. "Investigating negative-regulated target genes, we found eight genes (ANKRD13C, ARL5A, ATL3, PAWR, PDCD6IP, SLC16A7, TFAM, UBP1) presenting a significant inverse correlation with miR-181a/b expression also in melanoma A375 sensitive cells." (PMID 33670365, 2021).